CCR2 (C-C motif chemokine receptor 2)
Diseases named in the same sentence as CCR2 in open-access papers (continued):
Sharing a sentence is not in itself a finding about the gene and the disease.
tumor (continued). "In fact, AHR promotes CCR2 expression in TAMs and drives their infiltration into the tumor site, as well as CD39 expression, promoting CD8 T-cell dysfunction." (PMID 33766119, 2021). "In a recent study, it has been proven that CCR2 is involved in the recruitment and initiation of tumor-promoting inflammation." (PMID 33919517, 2021). "Binding of MCP-1 to its receptor CCR2 on tumour cells enhances tumour cell proliferation, migration, invasion, and angiogenesis, partly through activation of the ERK signalling cascade and secretion of proteases." (PMID 34223877, 2021). "The correlation between CCR2 and tumor‐infiltrating immune cells (TICs) was analyzed, and 14 kinds of TICs were found closely correlated with CCR2 expression through difference analysis." (PMID 33949150, 2021). "Based on the TCGA database, we investigated that the transcriptome level of CCR2 is abnormally reduced in tumor tissues." (PMID 34251980, 2021). "According to the literature, CCR2 can enhance the monitoring of the immune system and play a role in tumor resistance by triggering the TH1 response and recruiting CD8+ cells." (PMID 34250091, 2021). "FAP+CAFs were the main source of CCL2, which facilitated the recruitment of myeloid-derived suppressor cells (MDSCs) to the tumor and promoted immunosuppression in a CCR2 dependent manner." (PMID 34336660, 2021). "In patients with pancreatic adenocarcinoma, blockade of CCR2 prevented the accumulation of TAM in tumour sites but led to a compensatory CXCR2+ TANs influx, which possibly limited the intended treatment efficacy." (PMID 34464477, 2021). "We present here that beneficial effects of CCR2 antagonism in the tumor setting extend beyond blocking chemotaxis of suppressive myeloid cells." (PMID 34804061, 2021). "Previous studies in mouse tumour models of post-surgical adjuvant therapy demonstrated that an increase in Ang-2–mediated ICAM-1 expression contributed to the observed increase in CCL2-induced recruitment of tumour-promoting CCR2+Tie2− macrophages." (PMID 33564135, 2021). "The TIMER dataset was utilized to identify the correlations of CCR2 with immune infiltrating cells and tumor purity." (PMID 34251980, 2021). "Targeting the CCR2/CCL2 pathway showed effectiveness in other tumor models as it suppresses tumor progression." (PMID 32668709, 2020). "We focused on analyzing the role of CCR2-MCP-1 signaling in the recruitment of CCR2+ MDSCs into the tumor microenvironment using syngeneic, immunocompetent mice." (PMID 33322474, 2020). "Immunostaining of cleaved CASP-3 and TdT-mediated dUTP nick end labeling (TUNEL) indicated the activation of pro-death signaling in tumor cells, while Ki67 staining verified tumor suppression in CCR2−/− mice." (PMID 32103760, 2020). "Knockout of the chemokine ligand 2 (CCL2) receptor (CCR2) in mice significantly diminished PNI of prostate and PDAC cells compared with wild-type controls, revealing that CCL2–CCR2 signaling is a key mechanism of tumor–nerve communication." (PMID 33322770, 2020). "Inset = 60X image identifying CCR2+ neutrophils in the VI of a tumor animal, indicated by asterisks." (PMID 32391790, 2020). "Protein-protein interaction (PPI) and Cox regression analysis were performed on the differentially expressed genes (DEGs) to identify four key tumor microenvironment (TME) -related genes (CCR2, CCR4, P2RY12, and P2RY13)." (PMID 33318300, 2020). "The decrease in myeloid cell recruitment has previously been observed in Ccr2-knockout tumor models." (PMID 32668709, 2020). "In further studies, the effects of therapy with the CCR2 antagonist on anti-tumor cytotoxicity was determined by isolating T cells from draining lymph nodes at day 14 post-TC1 injection." (PMID 33322474, 2020). "In comparison with the CCR2+/+ animals, the numbers of F4/80+ TAMs and PD-1+ T cells in tumor microenvironment were markedly decreased in CCR2−/− mice." (PMID 32103760, 2020).
tumor (continued). "In various cancers, the crosstalk of TAMs with tumor cells via the CCL2/CCR2 axis play multiple roles in cancer development, such as monocyte/macrophage recruitment at the tumor site, tumor progression, EMT, invasion, and metastasis." (PMID 32219066, 2020). "The chemokine (C-C motif) ligand 2 (CCL2)/chemokine (C-C motif) receptor 2 (CCR2) signaling axis contributes to tumor progression through CCR2-mediated MDSC recruitment and/or accumulation." (PMID 31297636, 2020). "It has been reported that treatment with anti-CCR2 antibody can alleviate radiation-induced MDSCs infiltration in CRC tumor tissues by activation of the STING pathway." (PMID 33384962, 2020). "Endothelial progenitor cells expressing CCR2 can be recruited from the circulation in response to tumor expression of CCL2, contributing to tumor angiogenesis." (PMID 31690961, 2020). "Targeting CCR2+ TAM and CXCR2+ TAN in combination caused influx of both CD8+ and CD4+ T cells in the tumor microenvironment, improving antitumor immunity and reducing tumor burden." (PMID 31297636, 2020). "To understand the role of CCR2 within the tumor microenvironment, we used a suitable rodent tumor model in combination with Ccr2-/- mice." (PMID 32668709, 2020). "This progression is accompanied by reduced TAM accumulation, the strong proliferation of tumor cells, sufficient oxygen, and nutrient supply of the tumor tissue, ultimately supported by stabilized vasculature in Ccr2-/- mice." (PMID 32668709, 2020). "PDAC cells recruit immunosuppressive tumour-associated macrophages (TAMs) and myeloid-derived suppressor cells (MDSCs) from the peripheral circulation via the CCL2/CCR2 axis." (PMID 32061257, 2020). "Nevertheless, differential death pathway activation in KC leads to different recruitment of monocytes and monocyte-derived macrophages beneficial for tumor proliferation as the data from CCR2 KO mice confirmed." (PMID 33178579, 2020). "Histopathology imaging features of anatomic structures show that higher expression of STAT3, AHR, and CCR2 modules distinguishes between samples derived from the cellular tumor compared with those from leading edge and infiltrating tumor regions." (PMID 32383980, 2020). "Coordinating with myeloid cells penetrating into the tumor, myeloid-derived suppressor cells can also be recruited through the C-C chemokine receptor type 2 (CCR2)." (PMID 32411126, 2020). "High expression of CCR2 in MDSCs led to the aggregation of tumor-promoting monocytes, which was prevented by the simultaneous use of CCR2 antagonists." (PMID 32854711, 2020). "Our results show that Imaging-AMARETTO recapitulates known key drivers of tumor-associated microglia and macrophage mechanisms (STAT3, AHR, and CCR2) and neurodevelopmental and stemness mechanisms (OLIG2)." (PMID 32383980, 2020). "We next assessed what effects CCR2 deletion had on anti-tumor immune responses by harvesting tumors at 14 days post-injection, preparing single-cell suspensions and flow cytometric analysis." (PMID 33322474, 2020). "Taken together, this finding, the known tolerability in patients of CCR2-targeted therapies, and evidence that the combination is more effective across multiple tumor models, we believe clinical trials to be strongly justified." (PMID 33247183, 2020). "The expression of MCP-1, which is a ligand of CCR2, located on DC membranes was upregulated in epithelial cell-derived tumor cells." (PMID 33643911, 2020). "TAMs are believed to originate in the bone marrow as monocytes which are then recruited to the primary tumor via the CCL2/CCR2 signaling axis." (PMID 33374595, 2020). "Together, the inverse correlation of CD8+ CTLs with CCR2 and PD-1 suggested that TAMs mediate depletion of antitumor T cells and in consequence facilitates tumor cell evasion through PD-1 signaling pathway." (PMID 32103760, 2020). "The CCL2/CCR2 signaling is reported to be crucial for the development of TAMs and promotion of tumor growth in a rat glioma model." (PMID 32596397, 2020).
tumor (continued). "In animal experiments, CCL2 was shown to be responsible for increased tumor growth and metastasis due to the accumulation of CCR2-expressing macrophages." (PMID 32001710, 2020). "We found that the CCR2 antagonist markedly impaired tumor growth and significantly increased the T cell cytotoxicity." (PMID 33322474, 2020). "M-MDSCs and inflammatory monocytes migrate to the tumor site via the CCL2/CCR2 pathways and differentiated into TAMs in response to various factors secreted by tumor cells." (PMID 33384962, 2020). "Here we show across multiple murine tumor and metastasis models that CCR2 antagonism in combination with anti-PD-1 therapy leads to sensitization and enhanced tumor response over anti-PD-1 monotherapy." (PMID 33247183, 2020). "Genetic and pharmacological intervention of CCR2-MCP-1 signaling significantly decreased tumor growth in conjunction with increased effector cytotoxic CD8+ T cells." (PMID 33322474, 2020). "In many cases, ACKR2 inhibited the infiltration of tumor-supporting leukocytes, angiogenesis or tumor cell invasion; often, these processes were accompanied by reduced levels of the relevant chemokines and competition with CCR2-mediated signaling." (PMID 32582148, 2020). "Compared with non-polarized M0 macrophages, pro-inflammatory phenotype M1 macrophages overexpressed surface chemokine receptors i.e. CCR2, leading to a strong recruitment to the site of tumor though chemotactic attraction." (PMID 32550891, 2020). "Later studies further explore the pivotal role of CCR2 in directing the recruitment of CCR2+ monocytic cells to the tumor site to support its development and suppress antitumor immunity." (PMID 33193327, 2020). "Although both FOLFIRINOX and gemcitabine combined with nab-paclitaxel improve patient survival and disease response compared with single-agent gemcitabine, there is an immunosuppressive tumor microenvironment directed in part by the CCL2/CCR2 axis." (PMID 31297636, 2020). "Although CCL2 receptor (Ccr2) was suppressed in vitro by inflammatory signals, it was elevated in tumor tissues." (PMID 32244522, 2020). "This study analyzed the role of CCR2-MCP-1 signaling in the recruitment of CCR2+ MDSCs into the tumor microenvironment in syngeneic, immunocompetent mice." (PMID 33322474, 2020). "We found that mice that had rejected the TC1 tumors in response to therapy with a CCR2 antagonist in the first round of tumor studies had developed potent memory responses and showed complete inhibition of growth of tumors upon re-challenge." (PMID 33322474, 2020). "CD180, as well as CCR2, has been identified as robust pharmacodynamic tumor and blood biomarkers for clinical use with BRD4/BET inhibitors." (PMID 33082842, 2020). "Tumor cells recruited CCR2+ MDSCs through their expression of high levels of MCP-1/CCL2, the ligand for chemokine CCR2." (PMID 33322474, 2020). "The production of inflammatory cytokines such as PDGF, TNFa, CCR8, and CCR2 within the solid organ tumor microenvironment, has been shown to enhance homing of MSCs to the tumor location." (PMID 34713241, 2020). "The chemokine MCP-1 (CCL2) is important for the recruitment of bone marrow generated myeloid cells into the blood, and for the trafficking of MDSCs to tumor sites, by binding to the G protein-coupled receptor, CCR2." (PMID 33322474, 2020). "Consistent with higher secretion of CCL2 and Vegfα, upon orthotopic tumor engraftment, the TME of Rb-depleted cells showed higher angiogenesis and infiltration of CCR2-positive tumor-associated macrophages (TAMs) and MDSCs." (PMID 32244804, 2020). "M-MDSCs have been shown to depend on CCR2-mediated signals in regulating the entry of CD8+ T cells into the tumor site in melanoma patients." (PMID 32443699, 2020). "As expected, Tim-4– TAMs remained limited in Ccr2–/– tumor-bearing mice as compared with Ccr2+/+ mice." (PMID 32780724, 2020).
tumor (continued). "We next sought to create a system to test and validate the effects of a CCR2 antagonist on recruitment of inflammatory monocytes, given potential translational significance for tumor therapy." (PMID 33322474, 2020). "In fact, Hutter and colleagues used a Ccr2 knockout mouse model which limits MΦ infiltration into the tumor site, enabling the specific study of MG within the GBM iTME." (PMID 33117364, 2020). "The CCL2 and CCR2 signaling pathway mediates peripheral monocyte trafficking into the tumor microenvironment." (PMID 32780724, 2020). "Although we observed a drop of CD14 + CCR2+ IM in peripheral blood, a decrease of CCR2+ TAM in the tumor was only observed for two patients and is inadequate to support a definitive conclusion about this component of the mechanism of action." (PMID 31297636, 2020). "Flow cytometric analyses revealed only minor expression of CCR2 on myeloid cells (CD11b+CD45+) in naïve mouse brains while CCR2 was up-regulated in tumor-bearing mice." (PMID 32668709, 2020). "We observed a similar number of total peritoneal macrophages in tumor-free Ccr2–/– and Ccr2+/+ mice." (PMID 32780724, 2020). "Once again, combination therapy with CCR2 antagonist and anti-PD-1 is more efficacious than monotherapy in reducing tumor growth." (PMID 33247183, 2020). "The majority of macrophages present in the tumor microenvironment are recruited from bone marrow-derived monocytes through the CC chemokine 2 (CCL2/CCR2) and colony stimulating factor 1 (CSF-1/CSF-1R) signaling pathways." (PMID 32326073, 2020). "Seeking data of potential translational significance, we returned to our original immuno-oncology focus and assessed the effects of the CCR2 antagonist on the growth of TC1 tumor cells in syngeneic WT mice." (PMID 33322474, 2020). "After knocking out CCR2 in mice, the macrophages accumulation in tumors is decreased, slowing down the tumor growth." (PMID 33224886, 2020). "Circulating neutrophils in sham animals did not express CCR2, but a small percentage of circulating neutrophils expressed CCR2 in tumor animals, suggesting that the presence of a tumor induces CCR2 expression in neutrophils." (PMID 32391790, 2020). "PF-04136309 is a CCR2 inhibitor that, in combination with Folfirinox, resulted in local tumor control in pancreatic cancer patients." (PMID 32326073, 2020). "This chemokine binds to C-C chemokine receptor type 2 (CCR2) on monocytes and macrophages and attracts them to the tumor." (PMID 33066357, 2020). "Alternatively, there was a large increase in CCR2+ neutrophils in the brains of tumor-bearing animals." (PMID 32391790, 2020). "Herein, MSLN CAR T-cells that expressed a tumor homing chemokine receptor CCR2 showed improved tumor infiltration." (PMID 32582537, 2020). "Even if PDL1 is unchanged in the IBA1 cell population, we observed an overall increase of PDL1 expression in the tumor tissue of Ccr2-/- mice." (PMID 32668709, 2020). "Further work is required to delineate the roles of host-derived CCL2 and tumor-derived CCL2 in PCa tumorigenesis and metastasis, and to elucidate the downstream signaling molecules which mediate the effect of CCR2 signaling in tumor promotion." (PMID 32471499, 2020). "Altogether, these findings provide a plausible mechanism for CCL2 in the recruitment of CCR2-expressing myeloid cells subsets to the tumor, thus promoting macrophage tumor infiltration and macrophage-mediated development of lymphatic metastasis." (PMID 31811337, 2020). "CCL2 is expressed in tumors and affects endothelial permeability and metastasis through interacting with CCR2 expressed on tumor endothelial cells." (PMID 31690961, 2020). "For example, preclinical studies showed that targeting CCL2 or the CCL2 receptor (CCR2) on tumor infiltrating macrophages improved chemotherapeutic efficacy, inhibited metastasis and increased anti-tumor T-cell responses." (PMID 33059744, 2020).
tumor (continued). "Both the tissue resident macrophages present in normal mammary tissues and TAMs that develop during tumor progression in the MMTV-PyMT breast cancer model are derived from blood-circulating CCR2+ monocytes, but only TAMs display self-renewal capability." (PMID 32471499, 2020). "Monocytic MDSCs and inflammatory monocytes migrate to the tumor area via the CCL2/CCR2 and CSF pathways and are differentiated into TAMs through various factors secreted by tumor cells." (PMID 32726950, 2020). "As shown by the increased IVIS luminescence detection, overexpression of ERα in A549 cells can increase the tumor growth, which can be reduced by CCR2 antagonist, CXCR4 antagonist AMD3100, or anti‐estrogen fulvestrant in vivo." (PMID 32356397, 2020). "Next, we showed that deletion of the corresponding receptor (Ccr2) from the host of allografted tumours decreased macrophage infiltration." (PMID 31160587, 2019). "CXCL12 and CCL2 can promote angiogenesis and inhibit apoptosis of endothelial cells by directly binding their receptor (CXCR4 and CCR2, respectively) expressed on tumor vessels or indirectly promoting the recruitment of leukocytes." (PMID 30894861, 2019). "CCL2 interaction with its cognate receptor CCR2 promotes PCa tumour growth by sustaining macrophage infiltration and angiogenesis." (PMID 31718684, 2019). "Another group tested a CCR2 antagonist in vivo in a subcutaneous tumor model, where treatment led to decreased production of M2 cytokines and chemokines by TAMs." (PMID 31921102, 2019). "MSCs isolated from spontaneous lymphomas in mouse (L-MSCs) strikingly enhanced tumor growth in comparison to BM-MSCs, by recruiting monocytes/macrophages via the CCR2 signal." (PMID 31130595, 2019). "Accumulated documents indicated that the CCL2/CCR2 axis is an important mediator in the interactions between tumor cells and TAMs." (PMID 31024838, 2019). "The binding to its receptor CCR2 leads to the differentiation of monocytes into TAMs and to the subsequent promotion of their pro-tumoral activity, tumor cell proliferation, angiogenesis and metastatic dissemination." (PMID 31060337, 2019). "Antagonism of CCR2 by the compound RDC018 not only reduced TAM infiltration but also restored anti-tumor immune response and ameliorated HCC outcome in murine models of HCC." (PMID 31068952, 2019). "Accumulated studies indicated that CCL2 promoted the recruitment of TAMs via activating its receptor CCR2 in the process of tumor invasion and metastasis." (PMID 31024838, 2019). "Therapies are being developed that target CCL2/CCR2 and tumor resident myeloid cells, and clinical trials are being pursued that use these therapies as part of the treatment regimen." (PMID 31823764, 2019). "They found a specific accumulation of CCR2+ TAMs at the stroma/tumor interface in resected human HCCs, where they co-localize with endothelial cells in areas of intense vascularization." (PMID 31377844, 2019). "In a preclinical model, the oral CCR2 inhibitor PF-04136309 reduced the number of TAMs and exerted a modest effect on tumor growth when used alone, while it acted synergistically with the chemotherapeutic drug Gemcitabine (GEM)." (PMID 30894861, 2019). "One study showed that circulating NK cells recruited to the tumor stroma express atypical chemokine receptor 2 (CCR2), which suppresses CCR2 expression in KLRG1-expressing NK cells and limits their movement within the lungs towards other metastatic deposits." (PMID 30917934, 2019). "Recent studies demonstrated that the CCL2/CCR2 axis is responsible for the M2 polarization of TAMs, thereby shaping a tumor-supportive environment." (PMID 31024838, 2019). "Blockade of CCL2/CCR2 signaling that inhibits tumor-infiltrating macrophages the switch towards a pro-tumor M2 phenotype, suppresses murine liver tumor growth via activating T cell antitumor immune response." (PMID 31572568, 2019).